EPCAM (epithelial cell adhesion molecule)
Diseases named in the same sentence as EPCAM in open-access papers (continued):
Sharing a sentence is not in itself a finding about the gene and the disease.
bladder transitional cell carcinoma (4 papers, 2021 to 2024). The most common morphologic subtype of urinary bladder carcinoma (over 90% of cases). "The epithelial cell adhesion molecule (EpCaM), which is involved in upregulating c‐myc and cyclins A/B,146 is expressed in many tumor tissues, including urothelial carcinoma of the bladder." (PMID 38037752, 2023).
brain cancer (4 papers, 2018 to 2025). A primary or metastatic malignant neoplasm affecting the brain. "This team then further exploited a bispecific strategy that conjugated TfRA1 with the epithelial cell adhesion molecule (EpCAM) to treat brain cancer metastases." (PMID 38474636, 2024). "The bispecific aptamer had higher binding to metastatic brain cancer cells than EpCAM and transferrin aptamers alone." (PMID 29301363, 2018).
breast adenocarcinoma (4 papers, 2018 to 2024). "Our recent analyses have demonstrated positive downregulation of CD24 and EpCAM expression after oregano administration and decreased expression of CD24 and CD44 after treatment with clove buds in chemically-induced mammary adenocarcinomas in rats." (PMID 30970626, 2019).
carcinosarcoma (4 papers, 2013 to 2024). A malignant tumor composed of a mixture of carcinomatous and sarcomatous elements. "EpCAM was however significantly associated with histologic type, and high EpCAM expression was observed in 84% of patients with endometrioid endometrial carcinoma compared to 64% and 56% of patients with serous endometrial carcinoma and carcinosarcomas, respectively (p = 0.002)." (PMID 32041116, 2020). "For solid cancers, other BiTEs have been developed, including those targeting EpCAM (for carcinomas and carcinosarcomas), PSMA (castrate-resistant prostate cancer) and CEA (gastrointestinal adenocarcinomas)." (PMID 39759138, 2024). "Cell lines established from patients harboring advanced and/or chemotherapy resistant carcinosarcoma were assessed for EpCAM expression as were free tumor cells and spheroids collected via thoracocentesis from a patient." (PMID 26474755, 2015). "We evaluated all five primary carcinosarcoma cancer cell lines for their sensitivity to NK and T-cells with a standard 4-h chromium (51Cr) release assay cytotoxicity using solitomab (EpCAM BiTE®) at a concentration of 1 μg/ml." (PMID 26474755, 2015). "Cell fusion and carcinosarcoma formation can probably help explain why in general the EpCAM+ cells in HPCa/Hs5 tumors are rare (i.e., ∼0.2% or less)." (PMID 23451107, 2013). "EpCAM is a known biomarker for poor prognosis across a range of carcinomas and carcinosarcomas." (PMID 39759138, 2024). "As a result patients with EpCAM expressing carcinosarcomas refractory to standard treatments maybe benefit from BiTE®-based immunotherapy." (PMID 26474755, 2015). "The data presented here demonstrate that EpCAM is expressed in the majority of carcinosarcomas evaluated (80 %) and that solitomab effectively induced ADCC and significant tumor death in carcinosarcoma cell lines expressing EpCAM that were incubated with PBL." (PMID 26474755, 2015). "Overexpression of epithelial cell adhesion molecule-1 (EpCAM), also known as TROP-1 or TACSTD1, is a known poor prognostic biomarker across a large number of carcinomas and carcinosarcomas." (PMID 26474755, 2015).
chronic pancreatitis (4 papers, 2011 to 2024). A chronic inflammatory process causing damage and fibrosis of the pancreatic parenchyma. "It is very likely that after and even before surgical resection for chronic pancreatitis, many different cell types including pancreatic epithelial cell types enter the blood circulation or peritoneal cavity and result in EpCAM detection." (PMID 21281486, 2011). "However, a high background expression of EpCAM mRNA was also found in both chronic pancreatitis and healthy volunteers, necessitating application of a cut-off to discriminate between EpCAM-positivity and negativity." (PMID 21281486, 2011). "A fifth explanation could be the high background expression of EpCAM mRNA in both chronic pancreatitis and healthy volunteers." (PMID 21281486, 2011). "Indeed, immunohistochemical studies have shown increased EpCAM in chronic pancreatitis." (PMID 21281486, 2011).
Crohn disease (4 papers, 2014 to 2024). A gastrointestinal disorder characterized by chronic inflammation involving all layers of the intestinal wall, noncaseating granulomas affecting the intestinal wall and regional lymph nodes, and transmural fibrosis. "It has been shown that EpCAM+EGFR+ cells were found in benign inflammatory colon diseases, such as Crohn disease." (PMID 36613466, 2022). "(A) ESRP1 transcript levels were measured in inflamed versus matched, non-inflamed intestinal biopsies from Crohn’s disease (CD) patients and normalized to EPCAM expression." (PMID 28975893, 2017).
endometrial tumors (4 papers, 2020 to 2022). "Therein, the manufactured chips were used to capture the circulating endometrial tumor cells lines with Hec 1A tested tumor cell after coating the anti-epithelial cell adhesion molecule (EpCAM)antibody." (PMID 33401451, 2021). "This, combined with the observed high proportion of endometrial tumors with positive EpCAM staining in our cohort, suggests EpCAM as a potential biomarker for IGS that should be further explored in future studies." (PMID 32041116, 2020).
gastrointestinal carcinomas (4 papers, 2009 to 2021). "EpCAM is an antigen expressed on most normal epithelial cells as well as in gastrointestinal carcinomas." (PMID 34790117, 2021). "EpCAM is expressed by most epithelial cell membranes and in gastrointestinal carcinomas." (PMID 21092330, 2010). "However, since EpCAM is also expressed in normal human epithelial cells as well as in gastrointestinal carcinomas, we carried out the next set of experiments to validate and quantitate the presence of functional CSCs in colonospheres (within the confines of an in vitro system)." (PMID 20691072, 2010).
laryngeal carcinoma (4 papers, 2013 to 2025). Carcinoma that arises from the laryngeal epithelium. "In our experiments, the role of EpCAM in laryngeal cancer cell proliferation, cell invasion and migration were also confirmed." (PMID 40778224, 2025). "The expression of EpCAM was shown to be high in laryngeal carcinoma but low in bone marrow as a metastatic niche for disseminated cancer cells." (PMID 31443698, 2019). "Next, single cells were retrieved from larynx carcinoma biopsy, which displayed an intermediate to strong expression of EpCAM in approximately 95–100% of cells." (PMID 23383219, 2013).
prostate (4 papers, 2008 to 2021). "However, cell lines show 1–2 times higher expression of EpCAM and EGFR, considering all tumour types together or colon, breast and prostate tumoursindependently." (PMID 27711186, 2016).
skin tumors (4 papers, 2017 to 2026). "Merkel cell carcinoma (MCC) is a notoriously refractory type of skin cancer that expresses EpCAM." (PMID 40243928, 2025). "Merkel cell carcinoma (MCC) is a rare EpCAM-expressing refractory skin cancer." (PMID 40243928, 2025).
teratoma (4 papers, 2018 to 2022). A non-seminomatous germ cell tumor characterized by the presence of various tissues which correspond to the different germinal layers (endoderm, mesoderm, and ectoderm). "Upon differentiation of APCs toward committed young astrocytes there were no remaining undifferentiated cells, as shown by the levels of TRA-1-60, SSEA-4 and EPCAM, which remained < 0.1%, indicating high purity and low risk of teratoma formation." (PMID 29871694, 2018). "Transmembrane epithelial cell adhesion molecule (EpCAM) is expressed in epithelia, carcinoma, teratoma, and embryonic stem cells (ESCs)." (PMID 34693227, 2021). "The murine teratoma cell line mF9 was stably transfected with expression plasmids for murine EpCAM in fusion with yellow fluorescent protein (YFP) at the C-terminus and with YFP, as a control." (PMID 34693227, 2021). "In the present study, we have performed a proteomic interactome screen to identify potential binding partners of EpCAM in mouse teratoma cells with the aim to delineate pathways involved in regulation of EpCAM protein dynamics." (PMID 34693227, 2021). "EpCAM and ERas interaction was subsequently validated in independent co-immunoprecipitations of lysates from YFP- and EpCAM-YFP-expressing F9 teratoma cells and E14TG2α ESC." (PMID 29379062, 2018). "Upon transplantation, none of these EpCAM-/TNAP+ cells formed teratoma." (PMID 35676935, 2022).
thymoma (4 papers, 2017 to 2022). A neoplasm arising from the epithelial cells of the thymus. "EpCam(+) primary thymic epithelial cells (pTECs) established from resection specimens of thymomas showed higher cFLIP mRNA and protein levels than pTECs established from NTs at the time of sub-confluence and first passaging." (PMID 29163772, 2017).
tongue cancer (4 papers, 2022 to 2026). A malignant neoplasm affecting the tongue. "The observed trends suggest increased EpCAM overexpression in males, those with alcohol consumption, and tongue carcinomas, while a significant association was observed with higher histological grade." (PMID 42164196, 2026). "In tongue cancer, EpCAM expression was found to be substantially associated with tumor size, regional lymph node metastasis, histological differentiation, and invasion patterns." (PMID 40699639, 2025). "We obtained mechanistic data from EpCAM+/ABCG2+ CSCs of SCC-25 tongue cancer cell line but did not include equivalent primary CSCs in the study." (PMID 36248858, 2022).
Wilms tumor (4 papers, 2013 to 2021). An embryonal neoplasm characterized by the presence of epithelial, mesenchymal, and blastema components. "To exclude that the cultured stromal cells represent non-tumorigenic tumour-infiltrating fibroblasts, we obtained pure epithelial and stromal cells from a stromal-type Wilms tumour organoid culture (88T) based on EPCAM (epithelial) or THY1 (CD90, stromal) expression." (PMID 32161258, 2020). "Thus, Wilms tumor was the only pediatric cancer subtype which consisted of two coexisting tumor cell populations, with distinct immunophenotypes: CD45− CD56+ EpCAM+ CD90−vs. CD45− CD56+ CD90+ EpCAM−." (PMID 23472067, 2013). "Since all other non-carcinoma tumor cell samples (except one subset of tumor cells in the Wilms tumors) were negative for EpCAM, this marker could also be potentially useful for the diagnosis of this subtype of pediatric tumors, particularly if combined with CD90." (PMID 23472067, 2013). "Conversely, the two Wilms tumors showed two clearly distinct (coexisting) tumor cell populations with a common CD56+ and CD58+, CD45−, CD99−, GD2−, nuMYOD1−, numyogenin−, CD10− and NG2− phenotype, but distinct reactivity (negative versus positive expression) for CD90, EpCAM and CD57." (PMID 23472067, 2013).
adenomyosis (3 papers, 2018 to 2026). The growth of endometrial tissue inside the muscular wall of the uterine corpus. "In order to increase the credibility of our results, additional leiomyoma (n = 3) and adenomyosis (n = 3) samples were used to confirm EPCAM and PECAM1 colocalization and VM formation." (PMID 33685511, 2021). "Through single-cell RNA sequencing of adenomyosis tissues, we identified epithelial-endothelial transition (EET) as a key pathological mechanism and discovered transitional cells co-expressing epithelial (EPCAM) and endothelial (PECAM1) markers." (PMID 41861114, 2026).
ampullary cancer (3 papers, 2013 to 2025). "However, the loss of EpCAM is related to an aggressive tumor phenotype of ampullary cancer, which is different from other types of cancer." (PMID 25371063, 2015).
angiosarcoma (3 papers, 2016 to 2024). A malignant tumor arising from the endothelial cells of the blood vessels. "Tumours were also completely negative for the epithelial marker EpCAM, but scattered cells within the 129/Sv subcutaneous tumours, as well as rare cells in angiosarcomas in SCID/beige mice, reacted with a pan-CYTOKERATIN antibody, another epithelial marker." (PMID 29731980, 2018).
basaloid squamous cell carcinoma (3 papers, 2017 to 2023). A squamous cell carcinoma characterized by the presence of cells with hyperchromatic nuclei, scant amount of cytoplasm, and peripheral nuclear palisading. "For example, basal cell carcinomas of the skin with squamous metaplasia have higher EpCAM expression than basaloid squamous cell carcinomas." (PMID 37627911, 2023).
bone metastasis (3 papers, 2019 to 2024). Transfer of a neoplasm from its primary site to bones. "Third, the studies regarding the associations of EpCAM overexpression with bone metastasis and biochemical recurrence free-survival were relatively small." (PMID 31324239, 2019). "In a meta-analysis, EPCAM overexpression was associated with a higher risk of BCR and the development of bone metastasis." (PMID 38052461, 2024).
cervical squamous cell carcinoma (3 papers, 2015 to 2021). A squamous cell carcinoma arising from the cervical epithelium. "Using a novel approach, we isolated RNA from flow-sorted viable EpCAM+ tumor epithelial cells and CD45+ tumor-infiltrating immune cells obtained from squamous cell cervical cancer samples (n = 24)." (PMID 26299617, 2015). "Additionally, the negative correlation between Slug and EpCAM expression in cervical squamous cell carcinoma and endocervical adenocarcinoma (CESC) was confirmed from the GEPIA online database." (PMID 33691694, 2021).
Endometrioid carcinoma (3 papers, 2020 to 2022). "Endometrioid carcinoma from the endometrium and serous papillary and clear cell carcinomas from the ovary showed also strong EPCAM expressions." (PMID 33003511, 2020). "The significantly increased expression of ALDH1 and epithelial cell adhesion molecule (EpCAM) as well as Oct4, Nanog, Sox2 and Myc was also revealed in a CD133+ cell subpopulation isolated from an endometrioid adenocarcinoma." (PMID 35328833, 2022).
gynecological cancer (3 papers, 2011 to 2023). "CD1, an epithelial mesenchymal transition marker, along with the epithelial marker EpCAM, helped to facilitate the detection, monitoring, and prognostication of gynecologic cancer." (PMID 36768623, 2023). "CTC presence analyzed with Adna Breast Test (detection of EpCAM-, MUC-1-, and HER-2-transcripts) together with CA 125 assessment were shown to be of prognostic significance in gynecological cancers." (PMID 21827674, 2011).
hypopharynx carcinoma (3 papers, 2018 to 2026). A primary or metastatic malignant neoplasm that affects the hypopharynx. "It was reported that the strength and pattern of EpCAM expression are both positively correlated with the proliferation marker Ki-67, high expression and nuclear localisation of cyclin D1, and Rb phosphorylation in hypopharynx carcinoma in vivo, further validating its role in tumorigenesis." (PMID 30419852, 2018). "CRISPR-Cas9 mediated EpCAM knockout in FaDu hypopharynx carcinoma cell line showed no notable effect on cell-matrix or cell-cell adhesion." (PMID 32046162, 2020). "Furthermore, CRISPR-Cas9 mediated EpCAM knockout in FaDu hypopharynx carcinoma cell line showed no notable effect on cell-matrix or cell-cell adhesion property." (PMID 32046162, 2020).
influenza (3 papers, 2020 to 2021). An acute viral infection of the respiratory tract, occurring in isolated cases, in epidemics, or in pandemics; it is caused by serologically different strains of viruses (influenzaviruses) designated A, B, and C, has a 3-day incubation period, and usually lasts for 3 to 10 days. "Flow cytometry analysis of lung single-cell suspensions on day 60 after influenza infection revealed an increased percentage of alveolar epithelial type 2 (AT2) cells (CD45–T1α–CD31–EpCAM+/CD326+MHCII+) and endothelial cells (CD45–T1α–EpCAM–/CD326–CD31+) (respectively) compared with the naive state." (PMID 33600379, 2021). "ECs exhibited demonstrable but low levels of EdU incorporation (CD45−/EpCAM−/CD31+/EdU+) under uninjured conditions, but by day 27, ~20% were EdU+, indicating that, at minimum, 15% of the ECs were newly generated after influenza injury." (PMID 33239293, 2020).
invasive ductal breast carcinoma (3 papers, 2013 to 2017). The most common type of invasive breast carcinoma, accounting for approximately 70% of breast carcinomas. "A recent paper has shown that 80% of invasive ductal breast carcinomas are EpCAM positive." (PMID 23460885, 2013).
leiomyosarcoma (3 papers, 2015 to 2024). An uncommon, aggressive malignant smooth muscle neoplasm, usually occurring in post-menopausal women. "EPCAM was upregulated in lung metastases of leiomyosarcoma, suggesting inhibition of CD8+ T cell migration." (PMID 38291183, 2024). "Immunohistochemical staining revealed EpCAM protein expression in a subset of angiosarcomas and leiomyosarcomas and in all the osteosarcomas analyzed; in addition, a negative prognostic marker for leiomyosarcoma patients has been suggested." (PMID 26167450, 2015). "Our findings suggest that EPCAM could serve as a potential novel therapeutic target for leiomyosarcoma." (PMID 38291183, 2024).
malignant mesothelioma (3 papers, 2013 to 2024). A malignant neoplasm of the pleura or peritoneum, arising from mesothelial cells. "In summary, our data provide a comprehensive overview on EpCAM expression in cancer and confirm the suitability of EpCAM as a surrogate epithelial marker for adenocarcinomas and its diagnostic utility for the distinction of malignant mesotheliomas from pulmonary adenocarcinoma." (PMID 38786342, 2024). "EpCAM is expressed in many epithelial tumors and is used for the distinction of malignant mesotheliomas from adenocarcinomas and as a surrogate pan-epithelial marker." (PMID 38786342, 2024). "EpCAM positivity was seen in 16.7% of 24 epithelioid and in 30.2% of 53 biphasic malignant mesotheliomas where tumor cell staining was always limited to epithelioid cells." (PMID 38786342, 2024).
Merkel cell carcinoma (3 papers, 2017 to 2025). "Importantly, EpCAM-ReTARGTPRIFNαR149A potently induced the elimination of primary EpCAMpos refractory carcinoma cells from a Merkel cell carcinoma (MCC) patient." (PMID 40243928, 2025).
mismatch repair deficiency (3 papers, 2019 to 2024).
neuroendocrine carcinoma (3 papers, 2012 to 2021). A malignant neuroendocrine neoplasm composed of cells containing secretory granules that stain positive for NSE and chromogranin. "In a study of neuroendocrine cancer patients using CellSearch, CTCs were found in only 21-43% of the patients, although 100% of the tumours showed strong membrane EpCAM expression by IHC." (PMID 22591372, 2012). "In addition to epithelial neoplasms, neuroendocrine carcinomas from the lungs and pancreas displayed EPCAM expression." (PMID 33003511, 2020).
ovarian carcinosarcoma (3 papers, 2015 to 2022). A highly aggressive malignant neoplasm arising from the ovary. "Research reported that solitomab was a bispecific single-chain antibody construct targeting epithelial cell adhesion molecule on uterine and ovarian carcinosarcomas cells and might be an effective drug." (PMID 36114551, 2022). "We used flow cytometry to obtain highly sensitive measurements of EpCAM surface expression in two primary uterine carcinosarcoma cell lines (SARARK-1 and SARARK-9) and three primary ovarian carcinosarcoma cell lines (SARARK-3, SARARK-6 and SARARK-7)." (PMID 26474755, 2015).